NEUROD1 (neuronal differentiation 1)
Diseases named in the same sentence as NEUROD1 in open-access papers (continued):
Sharing a sentence is not in itself a finding about the gene and the disease.
pancreatic cancer (3 papers, 2022 to 2025). "Collectively, these results suggest that upregulation of NeuroD1 expression suppresses the proliferation of pancreatic cancer cells both in vitro and in vivo." (PMID 41225636, 2025). "NeuroD1-overexpressing pancreatic cancer cells appeared to undergo morphological alterations and to exhibit a neuron-like cell morphology." (PMID 41225636, 2025). "Through IF staining for the Ki-67 protein, which labels proliferating cells, and colony formation assays, we observed that NeuroD1 overexpression significantly decreased the proliferative capacity of pancreatic cancer cells." (PMID 41225636, 2025). "Transwell assays revealed that NeuroD1 also decreased the migratory ability of pancreatic cancer cells." (PMID 41225636, 2025). "Neuropathiazol upregulates NeuroD1 expression in pancreatic cancer cells and induces the transdifferentiation of pancreatic cancer cells into neurons." (PMID 41225636, 2025). "It suggests that upregulating NeuroD1 expression in pancreatic cancer cells via effective targeted drugs holds promise for inhibiting pancreatic cancer progression and offers new hope for pancreatic cancer treatment." (PMID 41225636, 2025). "In contrast, our findings revealed that the role of NeuroD1 in pancreatic cancer is mediated through Neurog3." (PMID 41225636, 2025). "We propose that NeuroD1-mediated neuronal transdifferentiation can significantly attenuate the malignant phenotype of pancreatic cancer." (PMID 41225636, 2025). "Based on this evidence, our study aimed to screen and identify key transcription factors (such as NeuroD1) that regulate the induction of transdifferentiation in pancreatic cancer cells." (PMID 41225636, 2025). "Given these limitations, it is imperative to identify more efficient and less toxic drugs that can effectively regulate NeuroD1 expression specifically in pancreatic cancer." (PMID 41225636, 2025). "The findings suggest that elevated NeuroD1 expression is correlated with increased differentiation of pancreatic cancer cells." (PMID 41225636, 2025). "Further hazard ratio (HR) analysis indicated that NeuroD1 serves as a protective factor in pancreatic cancer (HR < 1, P = 0.05)." (PMID 41225636, 2025). "Our study showed that NeuroD1 is a protective factor in pancreatic cancer, with high NeuroD1 expression correlating with improved patient outcomes." (PMID 41225636, 2025). "Collectively, these results imply that NeuroD1 facilitates the transdifferentiation of pancreatic cancer cells into neuron-like cells." (PMID 41225636, 2025). "Through drug screening analysis and experiments, we identified Neuropathiazol, a small-molecule compound that potentially induces the specific upregulation of NeuroD1 expression in pancreatic cancer cells." (PMID 41225636, 2025). "Both previous studies and our present work indicate that pancreatic cancer cells retain a certain degree of plasticity, allowing their conversion to a neuron-like phenotype induced by neural transcription factors such as NeuroD1." (PMID 41225636, 2025). "In parallel, we used the EZH2 inhibitor UNC1999 as a control to evaluate its impact on NeuroD1 expression in pancreatic cancer cells." (PMID 41225636, 2025). "In summary, our findings indicate that NeuroD1 interacts with Neurog3, and suppresses the proliferation of pancreatic cancer cells both in vitro and in vivo." (PMID 41225636, 2025). "We established subcutaneous tumor models by inoculating nude mice with Panc-1 and SW1990 cells and found that NeuroD1 overexpression hindered the progression of pancreatic cancer in vivo." (PMID 41225636, 2025). "The results indicated that highly differentiated pancreatic cancers presented reduced cell proliferation and increased NeuroD1 protein expression." (PMID 41225636, 2025). "NeuroD1 and Neurog3 induce the transdifferentiation of pancreatic cancer cells into cells with neuron-like phenotypes." (PMID 41225636, 2025).
pancreatic cancer (continued). "Our analyses of data from public databases preliminarily suggest that high expression of NeuroD1 is associated with a highly differentiated phenotype in pancreatic cancer and that NeuroD1 may function as a protective factor in pancreatic cancer." (PMID 41225636, 2025). "Furthermore, through RT-qPCR and Western Blotting experiments, we confirmed that the expression of Map2 and Tuj1 is upregulated in NeuroD1-overexpressing pancreatic cancer cells at both the gene and protein levels." (PMID 41225636, 2025). "This study aims to investigate whether inducing transdifferentiation in pancreatic cancer cells can reduce malignancy, focusing on the role of the transcription factor NeuroD1 and its regulatory pathways." (PMID 41225636, 2025). "NeuroD1 can induce the transformation of pancreatic cancer cells from a malignant phenotype to neurons with a benign phenotype; thus, screening for drugs that regulate and induce NeuroD1 expression may facilitate the treatment of pancreatic cancer." (PMID 41225636, 2025). "Neuropathiazol treatment also upregulated the expression of NeuroD1 in pancreatic cancer cells." (PMID 41225636, 2025). "Notably, the specific mechanism by which NeuroD1 drives the transdifferentiation of pancreatic cancer cells differs from that in other tumor types." (PMID 41225636, 2025). "However, in terms of inductive efficacy, NeuroD1 exhibits a significantly higher capacity than Neurog3 to induce pancreatic cancer cells to transdifferentiate into neuron-like phenotypes." (PMID 41225636, 2025). "Through a series of in vitro and in vivo experiments, our studies have demonstrated that the overexpression of NeuroD1 facilitates the transdifferentiation of pancreatic cancer cells into neuron-like cells and that it inhibits tumor cell proliferation and progression both in vivo and in vitro." (PMID 41225636, 2025). "While control tissues contained virtually no NeuN-positive cells, a significant proportion of NeuN-positive cells were found among the NeuroD1-overexpressing cells, suggesting that some of the pancreatic cancer cells had transdifferentiated into mature neuron-like cells." (PMID 41225636, 2025). "Our findings demonstrate that pancreatic cancer cells can be induced to transdifferentiate through NeuroD1 activation or pharmacological induction, suggesting a potential therapeutic strategy to mitigate malignancy by reprogramming tumor cells into less aggressive states." (PMID 41225636, 2025). "Next, we explored the specific role of NeuroD1 in pancreatic cancer." (PMID 41225636, 2025). "Our research suggests that NeuroD1 may represent a potential therapeutic target for pancreatic cancer, inducing the reversal of the malignant phenotype of pancreatic tumor cells via transdifferentiation into neurons through gene editing or the use of differentiation-inducing agents." (PMID 41225636, 2025). "Through a comprehensive series of in vitro and in vivo experiments, we discovered that NeuroD1 overexpression can induce the transdifferentiation of pancreatic cancer cells into neurons, thereby curbing tumor cell proliferation and migration and hindering pancreatic cancer progression in vivo." (PMID 41225636, 2025). "Among the pancreatic cancer cell lines, Panc-1 and SW1990 cells exhibited the lowest levels of NeuroD1 expression; using these cell lines, we established stable NeuroD1-overexpressing (OE) cell lines via lentiviral infection." (PMID 41225636, 2025). "Our findings revealed that UNC1999 did not affect the expression levels of NeuroD1 in pancreatic cancer." (PMID 41225636, 2025). "To date, no research has been reported on the role of NeuroD1 in the initiation and progression of pancreatic cancer." (PMID 41225636, 2025).
pancreatic cancer (continued). "IF staining for Map2 and Tuj1 revealed that in pancreatic cancer cells with low NeuroD1 expression, neither the control nor Neurog3-knockdown groups exhibited transition to a neuron-like phenotype, whereas Neurog3 overexpression partially induced this transition." (PMID 41225636, 2025).
Parkinson disease (3 papers, 2021 to 2024). A progressive degenerative disorder of the central nervous system characterized by loss of dopamine producing neurons in the substantia nigra and the presence of Lewy bodies in the substantia nigra and locus coeruleus. "Indeed, specifically blocking a subset of reactive astrocytes was shown to be neuroprotective in a model of Parkinson’s disease, and ectopic expression of Neurod1 in astrocytes may specifically decrease this reactive astrocyte population." (PMID 38540276, 2024). "How are NEUROD1 and NR0B1 and NR0B2 impacted in Parkinson’s disease?" (PMID 34941945, 2021).
retinal disease (3 papers, 2016 to 2025). "A majority of the significantly differentially expressed (FC > 2, FDR < 1%) genes show an increase in expression with higher glucose; these include genes involved in retina development (Neurod1, Casz1, and Crxos) or those associated with retinal disease (Impg1/2, Gucy2f, Mpp4, Arl6, and Rp1)." (PMID 40568109, 2025). "We examined whether transduction of additional transcription factors, RAX1 and NEUROD1, or modifications of the differentiation medium could increase the expression levels of retinal disease-related genes." (PMID 27170256, 2016). "Moreover, by modification of the culture conditions including additional transduction of RAX1 and NEUROD1, we found a greater variety of retinal disease-related genes than that observed in CRX-transduced PBMCs." (PMID 27170256, 2016). "Transduction of RAX1 and NeuroD1 in addition to CRX and modification of the differentiation medium facilitated induction of a greater variety of retinal disease-related genes." (PMID 27170256, 2016). "Several retinal disease-related genes absent in cells transduced with CRX alone were also significantly detected in cells transduced with CRX before NeuroD1 or those transduced with RAX1+CRX before NeuroD1 in a modified medium containing Activin A, Dkk, and Lefty2 or the RPE-conditioned medium." (PMID 27170256, 2016).
Glucose intolerance (2 papers, 2017 to 2025). Glucose intolerance (GI) can be defined as dysglycemia that comprises both prediabetes and diabetes. "PAK1 plays an unforeseen and beneficial role in beta cells by promoting insulin biogenesis via enhancing the expression of PDX1, NEUROD1 and INS, along with anti-apoptotic effects, that culminate in increased insulin content and beta cell mass in vivo and ameliorate diet-induced glucose intolerance." (PMID 39404845, 2025).
insulinoma (2 papers, 2019 to 2022). "All these comparisons highlighted several genes regulated only by NeuroD1, such pax4, rfx6, insm1a/b, genes reported to be direct targets of Neurod1 in human insulinoma cell line, therefore validating our experiments." (PMID 35286299, 2022).
lentivirus infection (2 papers, 2019 to 2024). Virus diseases caused by the Lentivirus genus. "Later, the Peng group presented contradictory data that NeuroD1 cannot convert microglia to neurons, but rather induces apoptosis in microglia, and that the “reprogrammed neurons” are in fact endogenous neurons that have been mislabeled by lentivirus infection." (PMID 39056804, 2024). "In the case of microglia-to-neuron reprogramming, this high level of NeuroD1 may not be enough, and an even higher level by repetitive lentivirus infection is required for successful reprogramming." (PMID 39056804, 2024).
neonatal diabetes mellitus (2 papers, 2022 to 2024). Neonatal diabetes mellitus presents as hyperglycemia, failure to thrive and, in some cases, dehydration and ketoacidosis which may be severe with coma, in a child within the first months of life. "Biallelic NEUROD1 mutations have been described in patients with permanent neonatal diabetes mellitus and severe neurological manifestations." (PMID 35769090, 2022).
neuroendocrine carcinoma (2 papers, 2022 to 2025). A malignant neuroendocrine neoplasm composed of cells containing secretory granules that stain positive for NSE and chromogranin. "ASCL1 is a transcription factor required for the proper development of pulmonary neuroendocrine cells while NEUROD1 is a neuronal/neuroendocrine protein that helps migration and survival of neuroendocrine carcinomas." (PMID 35263037, 2022).
pituitary tumor (2 papers, 2019 to 2021). A benign or malignant neoplasm affecting the pituitary gland. "Data from a number of methods (immunohistochemistry, confocal microscopy, and double label electron immunocytochemistry) suggest that NeuroD1 plays a key role in the pathogenesis of pituitary tumors, regardless of their hormonal state." (PMID 30719226, 2019). "However, when we removed the ChIP-seq data from the pituitary tumor line, which is arguably the closest to primary brain neurons, the BITFAM inference of increased NEUROD1 activity in selected populations was no longer associated with these cell types." (PMID 34193535, 2021).
subarachnoid hemorrhage (2 papers, 2023 to 2025). A serious neurological disorder characterized by intracranial hemorrhage into the subarachnoid space. "A study showed that NeuroD1 attenuates subarachnoid hemorrhage by attenuating reactive astrocyte‐mediated neuroinflammation and promoting astrocyte polarization to the A2 type." (PMID 40702752, 2025).
alcohol dependence (1 paper, 2021). Physical and psychological dependence on alcohol. "In order to probe for a relationship between reactive neurogenesis and alcohol dependence as has been observed in males, correlations were conducted between NeuroD1 profile counts and measures of withdrawal severity (peak/mean withdrawal scores) or BEC." (PMID 34594180, 2021). "In order to investigate whether ectopic neurogenesis is occurring in adult female rats after alcohol dependence, NeuroD1+ cells were also quantified in the outer 2/3 of the GCL, the hilus, and the molecular layer of the dentate gyrus at T14." (PMID 34594180, 2021).
Allergy (1 paper, 2019). An allergy is an immune response or reaction to substances that are usually not harmful. "Meanwhile, the combination of Tranilast (an anti-allergy drug) with Temo upregulated master neuronal TFs such as MYT1L and NEUROD1." (PMID 30837577, 2019).
Atrophy (1 paper, 2026). Any weakening or degeneration, especially through lack of use. "NeuroD1 AAV-based gene therapy prevents neuronal damage and degeneration, inhibits hippocampal atrophy, and reduces neuroinflammation in NHP AD models." (PMID 41806359, 2026).
bone metastasis (1 paper, 2022). Transfer of a neoplasm from its primary site to bones. "Meanwhile, brain and bone metastasis were less prevalent in patients classified into YAP1 subtype than those with ASCL1 subtype, respectively, and liver metastasis was decreased in YAP1 subtype than NEUROD1 subtype." (PMID 35311069, 2022).
brain cancer (1 paper, 2017). A primary or metastatic malignant neoplasm affecting the brain. "At least five of them (ARNT2, NEUROD1, NR1I2, HOXC9, NR4A2) are associated with brain cancer in previous studies." (PMID 29033978, 2017).
gastric tumors (1 paper, 2012). "NEUROD1 protein could be detected by Western blot in tumors from 85-day-old mice as well as in cell lines established from CEA424-SV40 TAg gastric tumors." (PMID 22253802, 2012).
gestational diabetes mellitus (1 paper, 2025). "Patient 3 carrying a NEUROD1 gene mutation (MODY6) was initially diagnosed with gestational diabetes mellitus (GDM)." (PMID 41020216, 2025).
glaucoma (1 paper, 2017). Increased pressure in the eyeball due to obstruction of the outflow of aqueous humor. "Moreover, NEUROD1 promotes the formation of early retinal ganglion cells, and retinal ganglion cell counts are associated with early visual field defects of glaucoma." (PMID 28484645, 2017).
injury (1 paper, 2021). Damage inflicted on the body as the direct or indirect result of an external force, with or without disruption of structural continuity. "Our findings suggest that the NeuroD1-based in vivo direct reprogramming technology may be a promising gene therapy treatment of brain injury by replenishing the lost neurons and successfully integrating them into the existing neural circuit." (PMID 34490268, 2021).
ischemia reperfusion injury (1 paper, 2020). Adverse functional, metabolic, or structural changes in ischemic tissues resulting from the restoration of blood flow to the tissue (reperfusion), including swelling; hemorrhage; necrosis; and damage from free radicals. "Therefore, our results suggest that NeuroD1 might be a downstream factor of exosomal miR-146b, which could promote the differentiation of endogenous neural stem cells in rats with ischemia-reperfusion injury." (PMID 32792909, 2020).
leukemia (1 paper, 2019). A malignant (clonal) hematologic disorder, involving hematopoietic stem cells and characterized by the presence of primitive or atypical myeloid or lymphoid cells in the bone marrow and the blood. "In a patient with leukemia, the average number of NeuroD1 expressing cells was much higher (case number 6)." (PMID 30719226, 2019).
liver diseases (1 paper, 2023). "Therefore, although further investigations are required, this study suggests that NeuroD1/GPX4 regulation may also be involved in other liver diseases." (PMID 38134213, 2023).
melanoma (1 paper, 2025). A malignant, usually aggressive tumor composed of atypical, neoplastic melanocytes. "In order to examine if melanoma cells can be transdifferentiated into neurons, the neuron-specific transcription factors ASCL1, BRN2, MYT1L, and NEUROD1 were ectopically overexpressed in different melanoma cell lines." (PMID 40715046, 2025). "For this purpose, we ectopically overexpressed the neuron-specific transcription factors ASCL1, BRN2, MYT1L, and NEUROD1 in melanoma cells." (PMID 40715046, 2025).
mental disorder (1 paper, 2017). A disease that has its basis in the disruption of mental process. "Last, is the EGR1-miR-30a-5p-NEUROD1 axis altered in patients with other psychiatric disorders?" (PMID 28072411, 2017).
non-small cell lung carcinoma (1 paper, 2025). A group of at least three distinct histological types of lung cancer, including non-small cell squamous cell carcinoma, adenocarcinoma, and large cell carcinoma. "However, regarding the functional importance of PDE2A as suggested by embryonic lethality of PDE2A knockout mice, PDE2A or miR-139-5p may play functional roles in the pathogenesis of NEUROD1-positive SCLC, as reported in non-small-cell lung cancer cells." (PMID 40595415, 2025).
pancreatic ductal adenocarcinoma (1 paper, 2025). An infiltrating adenocarcinoma that arises from the epithelial cells of the pancreas. "We then quantified the expression of NeuroD1 protein in another 120 pancreatic ductal adenocarcinomas present in patients treated at our center, categorizing them into high and low NeuroD1 expression groups." (PMID 41225636, 2025).